TGFB1 (transforming growth factor beta 1)
Diseases named in the same sentence as TGFB1 in open-access papers (continued):
Sharing a sentence is not in itself a finding about the gene and the disease.
preeclampsia (74 papers, 2009 to 2026). Preeclampsia is a hypertensive disorder of pregnancy that is characterized by new-onset hypertension with proteinuria presenting after 20 weeks of gestation, and depending on mild or severe forms may initially present with severe headache, visual disturbances, and hyperreflexia. "TGFβ1 tSNP rs4803457 genotype (CC vs. TT vs. CT) was also significantly associated with preeclampsia in the black subgroup (P = 0.01)." (PMID 23548068, 2013). "In black women, variation in two TGFβ1 tSNPs (rs4803455, rs4803457), one TGFβR1 tSNP (rs10739778), and three TGFβR2 tSNPs (rs6550005, rs1346907, rs877572) was associated with preeclampsia (P <0.05, each)." (PMID 23548068, 2013). "TGFβ1 levels were elevated in women with severe and mild preeclampsia late in gestation (mean gestational age, 40 weeks) compared with normotensive pregnant women." (PMID 38666946, 2024). "We observed an upregulation in interferon-gamma expression and a downregulation in transforming growth factor-beta-1 (TGF-β1), IL-4, and IL-10 in the placenta of patients with preeclampsia." (PMID 38894741, 2024). "A recent single-cell RNA-sequencing case–control study of preeclampsia, however, identified upregulation of TGFB1 in extravillous trophoblasts, potentially indicative of altered trophoblast differentiation or invasion." (PMID 36914823, 2023). "The results showed that the mRNA expression of TGFB1 and active TGF-β1 protein levels were increased in the placental tissues from preeclampsia patients compared with normal control groups." (PMID 30804321, 2019). "Transforming growth factor-beta 1 (TGF-β1) is thought to be involved in the pathogenesis of preeclampsia (PE), but the results are inconsistent among studies." (PMID 24823830, 2014). "Our results further suggest that the pathway’s involvement in preeclampsia differs in whites and blacks, with ENG and TGFBR2 being associated in whites and TGFβ1, TGFβR1, and TGFβR2 being associated in blacks." (PMID 23548068, 2013). "For black women, similar evaluation of TGFβ1 tSNP rs4803457 revealed women inheriting the CT genotype were 7.44 times more likely to develop preeclampsia than those with the CC genotype (P = 0.005, [99% CI: 1.19 to 46.41])." (PMID 23548068, 2013). "In contrast, it is reported that high TGFβ3 levels, but not TGFβ1 or TGFβ2 levels, can suppress trophoblast outgrowth, leading to shallow placental invasion and an increased risk of preeclampsia." (PMID 39791746, 2025). "TGFβ1 plays a decisive role in altering dNK (decidual natural killer) phenotype and function, which may have an obvious effect on the pathogenesis of preeclampsia." (PMID 38666946, 2024). "In the present study, CHEM, by increasing the expression of TGFβ1 protein in the endometrium, may contribute to the inadequate activation of NK cells and the development of preeclampsia." (PMID 35406725, 2022). "Cardiac gene expression of Vcam, Edn1, Ccr2, Ctgf, Tgfb1, Tgfb2, Tgfb3, Bnp, Cybb, Mmp2, Mmp9, Timp1, Camk2a, Slc9a1, Nr3c2, and Nr3c1 was not different between mice who had a normal pregnancy and mice who had a preeclampsia-like pregnancy at 5 or 10 weeks postpartum (respectively)." (PMID 40425613, 2025). "Preeclampsia also promoted TNF-α-, TGFβ1-, and VEGFA-induced proliferation of HUVEC from female offspring, but not in HUVEC from male offspring." (PMID 36420416, 2022). "We found that TGFB1 was upregulated in EOPE, which supports the elevated expression and serum levels of TGF-β1 in patients with preeclampsia." (PMID 34970543, 2021). "TGFβ-1, VEGF, IGF-1, and HTRA-1 are unique in that they have all been postulated to play a role in ROP and preeclampsia and have a direct and indirect role in angiogenesis." (PMID 33281553, 2020). "It has been reported that transforming growth factor beta-1 (TGFB1), a target of miR-33b-3p, may play a role in the pathogenesis of preeclampsia by preventing the differentiation of trophoblasts toward an invasive phenotype." (PMID 38338700, 2024).
preeclampsia (continued). "It has been shown that plasma TGFB1 and TGFB2 levels are elevated in patients with preeclampsia." (PMID 25478164, 2014). "Our exploratory examination in black women revealed that different genes from different components of the ENG pathway (TGFβ1 and TGFβR1, but not ENG) were associated with preeclampsia compared to white women." (PMID 23548068, 2013). "Excess TGFβ1 disrupts the balance of dNK subpopulations, suppresses vascular endothelial growth factor (VEGF) expression, and impairs spiral artery remodelling, all of which are key events in the pathogenesis of placental ischemia and, subsequently, preeclampsia." (PMID 41463175, 2025). "Moreover, there are also reports indicating that concentrations of TGFB1 in serum are indistinguishable between patients with preeclampsia and normal controls." (PMID 25478164, 2014). "Because TGFβ1 induces ENG expression and stimulates ENG promoter activity, genetic variation that affects the degree of TGFβ1 transmission may also explain differences in ENG expression (mRNA) between women with/without preeclampsia." (PMID 23548068, 2013). "Because two signaling pathways are known to modulate the profibrotic effects of MBG, a question arises whether the profibrotic effect of MBG may be initiated via SMAD-dependent TGFβ1 signaling, which was not the case for preeclampsia and CKD, where a key mechanism is Fli1 dependent." (PMID 39201581, 2024). "We found a statistically significant difference in average infant systemic HTRA-1, but not TGFβ-1, IGF-1, or VEGF-A relative to the presence or absence of ROP and maternal preeclampsia." (PMID 33281553, 2020). "Herein we show that HTRA-1, but not TGFβ-1, VEGF, or IGF-1, may mediate ROP protection in the setting of early-onset preeclampsia." (PMID 33281553, 2020).
type 1 diabetes (74 papers, 2005 to 2026). "Encapsulation of transforming growth factor-beta 1 (TGF-β1) within PLGA has also been demonstrated to attenuate immune rejection in the context of allogeneic islet transplantation for type 1 diabetes treatment." (PMID 38732722, 2024). "Inhibition of P2X7R decreases renal inflammation and improves functional parameters in the Streptozotocin mouse model of type 1 diabetes, whilst here, co-incubation of TGFβ1-treated primary hPTECs with a P2X7R antagonist (A438079) prevented NLRP3 activation." (PMID 37770948, 2023). "The combination of antigen (PPI) with the three immune response modifiers (TGFβ1, IL-10, and IL-2) is intended to induce antigen-specific Treg accumulating in the pancreas, and to preserve beta cell function in type 1 diabetes (T1D)." (PMID 37741949, 2023). "Interestingly, overexpression of Tgfb1 has been reported to improve autoimmune beta cell injury in a mouse model of type 1 diabetes." (PMID 40569436, 2025). "However, the relationship between TGFβ1 gene polymorphism and DR within type 1 diabetes is not demonstrated." (PMID 24710116, 2014). "However, at least as surprisingly, in several studies FOXP3 and other Treg-expressed molecules, such as TGFB1, have been found to be upregulated in the peripheral blood and intestinal mucosa of patients with CD and related conditions, for example, type 1 diabetes." (PMID 21392369, 2011).
oral cancer (73 papers, 2010 to 2026). "In an effort to elucidate the mechanism underlying the down-regulation of TGFBR3 in oral cancer cells, we identified an inverse relationship between the expression of TGFB1 and TGFBR3 using the TCGA-HNC database." (PMID 32471132, 2020). "We found that the rs1800469 SNP, a transforming growth factor beta-1 (TGFβ-1 −509 C/T) promoter polymorphism, showed protective effects in relation to oral cancer." (PMID 24278120, 2013). "During oral cancer progression, Snail mediated TGFβ1-induced MMP-9 expression via upregulating Ets-126." (PMID 29259250, 2017). "Accordingly, the TGFβ1/Smad 2/3 axis regulates MMP-9 expression through the transcriptional factors Snail and Ets-1, contributing to oral cancer progression." (PMID 20462450, 2010). "Screening of the data revealed eight TRGs (TGFB3, LTBP2, BMP2, TGFB1, ACVR1, CDK9, SLC20A1, and SMURF2) with non-zero coefficients, indicating their association with the prognosis of oral cancer patients." (PMID 38698292, 2025).
oral squamous cell carcinoma (72 papers, 2010 to 2025). "For instance, TGFβ1 stimulates THBS1 expression in oral squamous cell carcinoma (OSCC) cells." (PMID 32174791, 2020). "It has also been proposed that TGFB1 may influence the behavior of oral squamous cell carcinoma through mechanisms such as involvement in tumor fibrosis, epithelial-mesenchymal transition (EMT), and extracellular matrix remodeling, but few studies have reported on the role of TGFB1 in HNSCC." (PMID 36406133, 2022). "Thrombospondin 1 (THBS1), identified as an oncogene in oral squamous cell carcinoma (OSCC), acts as a tumor-specific extracellular matrix (ECM) protein induced by TGFB1." (PMID 38778403, 2024). "Studies have found that there are differences in the expression of TGFB1, SPP1 and other genes in oral squamous cell carcinoma (OSCC)." (PMID 31485443, 2019).
steatosis (72 papers, 2008 to 2025). Increased lipid within the cytoplasm of cells. "Another study involving adults treated with vitamin E (300 mg/d) for 1 year showcased improved steatosis and decreased transforming growth factor beta 1 (TGF-β1) levels." (PMID 38256169, 2024). "Inflammation, steatosis, ballooning, and fibrosis are the features of non-alcoholic fatty liver disease (NAFLD), and the associated critical bona fide genes such as MCP-1, TNF, TNFR1, TGFβ1, Colα1, αSMA, Timp1, and Hp were significantly enriched in the livers of mice fed an HFD." (PMID 31616013, 2019). "This was accompanied by steatosis, increased Bax/Bcl-2 ratio, and overexpression of p-SAPK/JNK, Tgfβ1, Map3k14, and Col1a1 in the liver." (PMID 34663892, 2022). "Praud C's results based on innovative histological techniques of fluorescence intensity measurements suggest that the balance between TGFB1 and PPARG is essential for fibrosis or steatosis induction." (PMID 35372563, 2022). "Furthermore, the expression of the fibrosis-related genes Col1a1, Tgfb1, and Timp1 was lower in the HY7207 group than in the ND group These data imply that HY7207 ameliorates hepatic lipid accumulation, steatosis, inflammation, and fibrosis in mice with NAFLD." (PMID 39337360, 2024). "This treatment had little effect on liver injury with significant hepatocyte necrosis and microvesicular steatosis observed in AOM-treated mice pretreated with anti-TGFβ1 or IgG1, and no apparent hepatic injury was observed in either vehicle group." (PMID 30940161, 2019). "Consistently, nine genes in the fatty acid metabolism, phospholipidosis and steatosis pathways including Acot2, Ugt2a1, Cd36 and Retn were upregulated in the cirrhotic liver post SPION injection accompanied with elevated Tgfb1 and sodium bile acid cotransporter (Slc10a1) of the cholestasis pathway." (PMID 27357559, 2016).
Hepatic steatosis (71 papers, 2008 to 2025). Steatosis is a term used to denote lipid accumulation within hepatocytes. "We found that miR-21a-5p expression was decreased in PFD group, as well as, Srebf1 and Tgfb1. miR-21a-5p hepatic diminution has been associated with improved glucose tolerance and insulin sensitivity, in addition to prevent hepatic steatosis and fatty acid absorption." (PMID 34083664, 2021). "BPA exacerbated hepatic steatosis in the OVX HBPA group, elevating lipid/collagen deposition with reduced Mttp mRNA and upregulated β-oxidation (Acox1, Acadvl), mitochondrial uncoupling (Ucp2), ER stress (Hyou1, Atf6), and liver injury (Tgfb1, Casp8) genes." (PMID 40475995, 2025).
silicosis (71 papers, 2009 to 2026). Silicosis is a respiratory disease caused by breathing in (inhaling) silica dust. "miR-99a-5p was significantly downregulated in the lung of a mice silicosis model and in TGFβ1-induced NIH-3T3 cells." (PMID 39684337, 2024).
diabetic cardiomyopathy (69 papers, 2013 to 2026). Diabetic cardiomyopathy is a disorder of the heart muscle in people with diabetes. "Consistent with findings from rats with diabetic cardiomyopathy, we observed a significant increase in ECM content with activation of TGFβ1/Smads signaling." (PMID 25884585, 2015).
chronic obstructive pulmonary disease (68 papers, 2007 to 2025). A chronic and progressive lung disorder characterized by the loss of elasticity of the bronchial tree and the air sacs, destruction of the air sacs wall, thickening of the bronchial wall, and mucous accumulation in the bronchial tree. "For example, among the 4 chronic obstructive pulmonary disease (COPD)–associated proteins shown in the network, TGFB1 is the direct target of HCoV-229E, and all 4 proteins (TGFB1, DEFB1, SNAI1, and ADAM33) interact with at least 1 SARS-CoV-2 target protein." (PMID 33156843, 2020).
coronary artery disease (68 papers, 2007 to 2026). "Genetic variations in TGFB1 gene have been studied in relation to coronary heart disease (CHD) risk, but the results were inconsistent." (PMID 22607024, 2012). "Also, in a Chinese population, TGFB1 rs1800469 and TGFB1 rs1800470 were associated with coronary artery disease." (PMID 36672663, 2023). "The aim of this paper was to analyse the relationship between polymorphisms in the TGFB1, PDGFB, bFGF, EGF and VEGF-A genes and ISR in patients with stable coronary artery disease (SCAD)." (PMID 26930482, 2016). "Individuals with increased risk for coronary artery disease presented reduced interleukin-1 (IL-1), IL-6, TNF-α, and C-reactive levels, together with improved IL-10 and transforming growth factor beta-1 systemic levels after an ET program." (PMID 25045207, 2014). "An important TGFβ1-related signaling cascade is activated in cardiac fibroblasts from patients with coronary artery disease when compared with controls, and the inhibition of IL11, a main downstream target of TGFβ1, leads to reduced fibrosis in the heart using murine model." (PMID 32664951, 2020). "In patients with symptomatic coronary artery disease (CAD), expression of transforming growth factor beta 1 (TGF-β1) on the platelet surface correlated with the expression of SDF-1α and SDF-1α receptors: CXCR4 and CXCR7." (PMID 34123416, 2021).
allergic asthma (67 papers, 2006 to 2026). A asthma with a basis in a pathological type I hypersensitivity reaction. "Both subsets are highly proinflammatory and express various inflammatory cytokines and mediators such as Il4, Il5, Il13, Tnfsf11, Areg, Tgfb1, Calca and Furin, all of which are implicated in promoting allergic asthma and other allergic diseases." (PMID 40089475, 2025). "In this scenario, it is thus inferred that TGFβ1 is implicated in the inception of allergic asthma by fostering the sensitization process." (PMID 17892594, 2007). "Our studies reveal a previously unidentified functional axis of AhR–RhoA in regulating TGFβ1 expression and signaling activation, representing a potential therapeutic target for allergic asthma." (PMID 33936062, 2021). "Huangqi-Fangfeng, the main components of YPFS, inhibited airway remodeling by regulating epithelial-derived transforming growth factor beta-1 (TGF-β1) in a house dust mite (HDM)-induced allergic asthma mouse model." (PMID 34305612, 2021). "Activation of TGFβ1 within the epithelium by the αvβ6 integrin plays a role in many diseases, including airway hyperresponsiveness in allergic asthma." (PMID 23547562, 2013). "In a murine model of allergic asthma, Tanaka and coworkers reported a positive correlation between the number of eosinophils and the level of TGFβ1 in whole-lung lavage fluid." (PMID 17892594, 2007). "Kumar and coworkers also suggested that the concentration of antigen and the number of antigen exposures are key elements determining which cells will preferentially produce TGFβ1 in allergic asthma." (PMID 17892594, 2007). "We note that airways infection with respiratory syncytial virus (RSV), the most common viral respiratory pathogen in small children which is widely considered as a risk factor for the development of allergic asthma later in life is characterized by an increased expression of SNAI1, MMP-2, and TGFβ1." (PMID 24228254, 2013). "They concluded that eosinophils are the main TGFβ1-producing cells in acute models of allergic asthma challenged with high doses of antigen, but the epithelium is the main source of this cytokine in sensitized animals chronically challenged with low doses of antigen." (PMID 17892594, 2007). "Given the important function of mast cells in the pathophysiology of allergic asthma, increased secretion of TGFβ1 by structural cells in the airways following allergic challenge may foster, rather than attenuate, inflammation." (PMID 17892594, 2007). "In a mouse model of allergic asthma, acute HDM exposure significantly increased TGFβ1 protein in the BAL fluid, decreased expression of CDH1 and occludin in the airway epithelium, and increased expression of VIM, αSMA and pro-collagen 1 in the mesenchyme." (PMID 36230980, 2022).
esophageal squamous cell carcinoma (67 papers, 2013 to 2025). Esophageal squamous cell carcinoma (ESCC) is a type of esophageal carcinoma (EC) that can affect any part of the esophagus, but is usually located in the upper or middle third. "The expression and activation of FOXO1 in esophageal squamous cell carcinoma induce TGFβ1 expression and make these cancer cells significantly resistant to chemotherapeutic agents." (PMID 38125769, 2023). "In our study we investigated the role of TGFβ1 on iCAF formation in esophageal squamous cell carcinoma (ESCC)." (PMID 34218518, 2021). "Knockdown of CDKN2B-AS1 increased the expression of p15 (INK4b) and transforming growth factor β1 (TGFβ1) resulting in the inhibition of cellular proliferation in human esophageal squamous cell carcinoma." (PMID 32825664, 2020). "Targeting the TGFβ1 pathway may be an effective therapeutic approach to improve the efficacy of cisplatin in esophageal squamous cell carcinoma." (PMID 36641471, 2023). "Several reports have identified that GREM1 amplifies TGFβ1 signaling to drive EMT in CRC and esophageal squamous cell carcinoma." (PMID 35883579, 2022). "We analyzed sequencing data of The Cancer Genome Atlas (TCGA) and our own previously established RNA microarray data (GSE53625), as well as esophageal squamous cell carcinoma (ESCC) cell lines with or without TGFβ1 stimulation." (PMID 34218518, 2021).
Granuloma (65 papers, 2009 to 2025). A compact, organized collection of mature mononuclear phagocytes, which may be but is not necessarily accompanied by accessory features such as necrosis. "Consistent with this, we found that although the mRNA expression of SMADs 2 and 3 were not elevated in FCMs, levels of phosphorylated, nuclear localised SMAD2 were increased in granuloma FCMs relative to NFMs and in plaque FCMs, suggesting that TGFβ1 signalling was occurring." (PMID 26197235, 2015).
metabolic syndrome (65 papers, 2009 to 2026). A cluster of metabolic risk factors for CARDIOVASCULAR DISEASES and TYPE 2 DIABETES MELLITUS. "A strong correlation was present between the AER and TGFβ1 in control and metabolic syndrome animals." (PMID 33562080, 2021).